NUP35 (nucleoporin 35)
Description:
Functions as a component of the nuclear pore complex (NPC). NPC components, collectively referred to as nucleoporins (NUPs), can play the role of both NPC structural components and of docking or interaction partners for transiently associated nuclear transport factors. May play a role in the association of MAD1 with the NPC.
Synonyms: MP-44; MP44; NUP53; NP44
Tractability: Antibody: UniProt places it where antibodies can reach, with high confidence; its Gene Ontology location is reachable by antibodies, with high confidence. PROTAC: ubiquitination databases record sites on it; its protein half-life has been measured.
Gene: Protein-coding gene on chromosome 2 (183,117,513 to 183,163,114, forward strand). Ensembl gene ENSG00000163002.
Subcellular location: Nucleus, nuclear pore complex; Nucleus membrane
Subcellular location (Human Protein Atlas): Nuclear membrane; Nucleoplasm; Plasma membrane
Pathways (Reactome):
Disease: Defective TPR may confer susceptibility towards thyroid papillary carcinoma (TPC); HCMV Early Events; HCMV Late Events; NEP/NS2 Interacts with the Cellular Export Machinery; NS1 Mediated Effects on Host Pathways; Nuclear import of Rev protein; Rev-mediated nuclear export of HIV RNA; SARS-CoV-2 activates/modulates innate and adaptive immune responses; Transport of Ribonucleoproteins into the Host Nucleus; Viral Messenger RNA Synthesis; Vpr-mediated nuclear import of PICs
Metabolism of RNA: Transport of Mature mRNA Derived from an Intronless Transcript; Transport of Mature mRNA derived from an Intron-Containing Transcript; Transport of the SLBP Dependant Mature mRNA; Transport of the SLBP independent Mature mRNA; snRNP Assembly; tRNA processing in the nucleus
Metabolism of proteins: SUMOylation of DNA damage response and repair proteins; SUMOylation of DNA replication proteins; SUMOylation of RNA binding proteins; SUMOylation of SUMOylation proteins; SUMOylation of chromatin organization proteins; SUMOylation of ubiquitinylation proteins
Metabolism: IP3 and IP4 transport between cytosol and nucleus; IP6 and IP7 transport between cytosol and nucleus; IPs transport between nucleus and cytosol; Regulation of Glucokinase by Glucokinase Regulatory Protein
Cell Cycle: Nuclear Pore Complex (NPC) Disassembly; Postmitotic nuclear pore complex (NPC) reformation
Cellular responses to stimuli: Regulation of HSF1-mediated heat shock response
Immune System: ISG15 antiviral mechanism
Gene Ontology:
Molecular function: protein binding; phospholipid binding; structural constituent of nuclear pore; identical protein binding; nucleic acid binding
Biological process: NLS-bearing protein import into nucleus; nuclear pore organization; nucleocytoplasmic transport
Cellular component: nuclear envelope; nuclear membrane; cytosol; nuclear pore; nuclear pore central transport channel; nuclear pore nuclear basket
Genetic constraint (gnomAD): Loss-of-function variants: 19 observed, 30.53 expected, observed/expected ratio (o/e) 0.62, 90% interval 0.43 to 0.91. The upper end of that interval is the gene's LOEUF score, 0.91, which puts it in group 3 of 6, group 1 being the genes least tolerant of losing a copy. Missense variants: 346 observed, 346.43 expected, observed/expected ratio (o/e) 1, 90% interval 0.91 to 1.09. Synonymous variants: 127 observed, 117.61 expected, observed/expected ratio (o/e) 1.08, 90% interval 0.93 to 1.25.
Homologues: Orthologues: chimpanzee NUP35 (100% identical), macaque NUP35 (99% identical), dog NUP35 (97% identical), pig NUP35 (97% identical), guinea pig NUP35 (95% identical), mouse Nup35 (93% identical), rat Nup35 (92% identical), rabbit NUP35 (90% identical), tropical clawed frog nup35 (72% identical), zebrafish nup35 (70% identical), Drosophila melanogaster Nup35 (30% identical), Caenorhabditis elegans npp-19 (25% identical).
Diseases named in the same sentence as NUP35 in open-access papers:
NUP35 is named in the same sentence as 7 diseases in open-access papers, as found by Europe PMC text mining. Sharing a sentence is not in itself a finding about the gene and the disease. The quoted sentences say what the papers report.
HIV-1 infection (1 paper, 2023). The type species of lentivirus and the etiologic agent of acquired immunodeficiency syndrome (AIDS). "Collectively, these data suggest the mechanisms underlying HIV-1 infection inhibition in Nup35-knockdown cells may be similar to the infection blocks encountered by A92E and G94D HIV-1 in normal cells in that CypA drives these viruses toward a nuclear entry pathway that they are unable to utilize." (PMID 37355754, 2023). "In order to better understand the interrelation between Nup35- and Nup155-dependent infection, we depleted both factors and assessed the effect of CsA treatment on HIV-1 infection." (PMID 37355754, 2023). "While knockdown of Nup35 specifically diminished WT HIV-1 infection in 2 of 3 shRNA lines, CsA treatment restored WT HIV-1 infectivity to levels observed in shRNA control cells treated with the drug." (PMID 37355754, 2023). "To gain insight into the specific stage of HIV-1 infection at which Nup35 and CsA exert their effects, we performed time course experiments on Nup35-knockdown HeLa cells that were treated with CsA at various times after exposure to virus." (PMID 37355754, 2023). "Consistent with the pooled siRNA results, two different siRNAs directed against Nup35, siRNA-2 and siRNA-3, reduced WT HIV-1 infection approximately 10-fold correlating with Nup35 depletion, whereas N74D HIV-1 and P90A HIV-1 were resistant to Nup35 depletion." (PMID 37355754, 2023). "Taken together, these data indicate that the block to HIV-1 infection in Nup35-depleted cells is dependent on the virus binding CypA." (PMID 37355754, 2023). "N74D HIV-1 infection was relatively consistent under the different Nup35 expression conditions." (PMID 37355754, 2023). "Notably, depletion of CypA not only restored HIV-1 infection in Nup35-knockdown cells but similarly restored infection in POM121-knockdown cells and partly restored infection in Nup153-knockdown cells." (PMID 37355754, 2023). "These cells expressing the suspected N-terminally truncated Nup35 had reduced susceptibility to HIV-1 infection but not N74D or P90A HIV-1 infection." (PMID 37355754, 2023). "To determine whether the effect of Nup35 on WT HIV-1 infection was direct, we sought to examine the stability of other Nups after Nup35 depletion with siRNA." (PMID 37355754, 2023). "Notably, coordinate depletion of Nup35 and Nup153 potently impaired WT HIV-1 infection." (PMID 37355754, 2023). "Nup35, Nup153, Nup358, and POM121 depletion were observed to inhibit WT HIV-1 infection but affected N74D and P90A HIV-1 infection to a lesser degree." (PMID 37355754, 2023). "Consistent with prior results, cells depleted for endogenous Nup35 and transduced with the LPCX empty vector were more than 10-fold less permissive to HIV-1 infection." (PMID 37355754, 2023). "Indeed, in cells depleted of Nup35, POM121, or Nup153, a partial restoration of WT HIV-1 infection is observed after coordinate knockdown of CPSF6, especially in Nup35 and POM121 knockdown cells." (PMID 37355754, 2023). "As the CypA knockdown data indicated, CsA treatment restores HIV-1 infection in Nup35 knockdown but not Nup155 knockdown cells." (PMID 37355754, 2023). "In Nup35-knockdown cells, WT HIV-1 infection no longer leads to CPSF6 precipitation in the nucleus." (PMID 37355754, 2023). "Because Nup35 and POM121 depletion affected WT HIV-1 infection but not CA mutant HIV-1 in a pattern similar to Nup153 and Nup358, we focused efforts on these two Nups." (PMID 37355754, 2023). "Furthermore, the functional rescue experiments showed that ectopically expressed Nup35 rescued WT HIV-1 infection, but not N74D HIV-1 infection in Nup35-knockout cell clones." (PMID 37355754, 2023).
schizophrenia (1 paper, 2018). A major psychotic disorder characterized by abnormalities in the perception or expression of reality. "This SNP maps near the pseudogene CACYBPP2, between the nucleoporin NUP35 and the zinc finger protein ZNF804A, a candidate for ASD, schizophrenia, and other neuropsychiatric disorders." (PMID 30134952, 2018).
type 2 diabetes mellitus (1 paper, 2023). A type of diabetes mellitus that is characterized by insulin resistance or desensitization and increased blood glucose levels. "We also found changes in the expression of nucleoporin genes such as NDC1, NUP35, NUP58, NUP107, NUP160, and POM121C in pancreatic beta cells of patients with type 2 diabetes mellitus." (PMID 37569434, 2023).
infection (2 papers, 2019 to 2023). The state of being infected such as from the introduction of a foreign agent such as serum, vaccine, antigenic substance or organism. "Because N74D HIV-1 and P90A HIV-1 were insensitive to Nup35 depletion, we examined other viruses with CA mutations that influence interaction with CPSF6 or CypA for infection of Nup35 knockdown cells." (PMID 37355754, 2023). "To examine the role of Nup35 FG dipeptides during infection, we depleted cells of endogenous Nup35 and ectopically expressed Nup35 with or without FG mutations." (PMID 37355754, 2023). "Similar to WT HIV-1, these viruses were impaired for infection of Nup35 and TNPO3 knockdown cells." (PMID 37355754, 2023). "Given the early reversibility of the infection block and the alteration of the nuclear pore complex by the various Nup knockdowns, we evaluated HIV-1 reverse transcription in cells depleted of Nup35 in the absence or presence of CsA." (PMID 37355754, 2023). "While HIV-1 was blocked for infection in Nup35 or POM121 knockdown cells, after treatment with CsA, HIV-1 enters the nucleus and infection is restored to levels of control cells." (PMID 37355754, 2023). "In comparison, expression of the third FG mutant did not restore WT infection in cells depleted of endogenous Nup35." (PMID 37355754, 2023). "Up to 12 h post-infection of Nup35-depleted cells, WT HIV-1 infectivity could be rescued by CsA treatment; however, CsA completely lost rescue ability at 24 h post-infection." (PMID 37355754, 2023). "Furthermore, the expression of two of these genes (NUP35 and OXCT1) was enriched in immune tissues implying a potentially pleiotropic effect or likely role in milk production during udder infection, which needs to be further elucidated in future studies." (PMID 31765378, 2019). "Notably, the small infection decrease in MLV infection occurring after Nup35 knockdown was not offset in cells expressing exogenous HA-Nup35 suggesting the effect on MLV could be indirect." (PMID 37355754, 2023). "While N57A and K70A HIV-1 were less sensitive to Nup35 depletion, Q63A/Q67A and T107A HIV-1 resembled WT HIV-1 in infection indicating that CPSF6-interaction on its own does not predict Nup35 dependence." (PMID 37355754, 2023).
cancer (1 paper, 2016). A tumor composed of atypical neoplastic, often pleomorphic cells that invade other tissues. "Finally, for DMRs whose associated genes had increased expression upon treatment with FQI1, we observed enrichment of GO terms for pathways in cancer (e.g. PIAS4, SMAD3, TRAF4, MAP2K1) and RNA transport (e.g. NUP188, EIF3A, NUP35, RAN) in both hyper and hypomethylated DMRs." (PMID 27845898, 2016).
NUP35 also shares sentences with these, for which no sentence is quoted: tumor (1 paper); viral infections (1).